TNPO3 (transportin 3)
Diseases named in the same sentence as TNPO3 in open-access papers (continued):
Sharing a sentence is not in itself a finding about the gene and the disease.
neuromuscular disease (1 paper, 2022). "Simultaneously, a heterozygous missense variant [NM_012470.3: c.2453G>A p.(Arg818Gln)] in TNPO3 was reported in a patient with no familial occurrence of neuromuscular diseases and no other mutations in genes associated with muscular disorders." (PMID 35309568, 2022).
TNPO3 also shares sentences with these, for which no sentence is quoted: Crohn disease (2 papers); systemic sclerosis (2); alopecia areata (1); ankylosing spondylitis (1); Dysarthria (1); leukemia (1); melanoma (1); myotonic dystrophies (1); neuroblastoma (1); pancreatic cancer (1); primary biliary cirrhosis (1); psoriasis (1); rheumatoid arthritis (1).